MYO6 (myosin VI)
Description:
Myosins are actin-based motor molecules with ATPase activity (By similarity). Unconventional myosins serve in intracellular movements (By similarity). Myosin 6 is a reverse-direction motor protein that moves towards the minus-end of actin filaments. Has slow rate of actin-activated ADP release due to weak ATP binding (By similarity). Functions in a variety of intracellular processes such as vesicular membrane trafficking and cell migration (By similarity). Appears to be involved in a very early step of clathrin-mediated endocytosis in polarized epithelial cells. Together with TOM1, mediates delivery of endocytic cargo to autophagosomes thereby promoting autophagosome maturation and driving fusion with lysosomes. Links TOM1 with autophagy receptors, such as TAX1BP1; CALCOCO2/NDP52 and OPTN. May act as a regulator of F-actin dynamics (By similarity). As part of the DISP complex, may regulate the association of septins with actin and thereby regulate the actin cytoskeleton. May play a role in transporting DAB2 from the plasma membrane to specific cellular targets (By similarity). May play a role in the extension and network organization of neurites (By similarity). Required for structural integrity of inner ear hair cells (By similarity). Required for the correct localization of CLIC5 and RDX at the stereocilium base (By similarity). Modulates RNA polymerase II-dependent transcription.
Synonyms: KIAA0389; DFNA22; DFNB37
Tractability: Small molecule: a structure with a bound ligand is known. Antibody: UniProt places it where antibodies can reach, with high confidence; its Gene Ontology location is reachable by antibodies, with high confidence. PROTAC: ubiquitination databases record sites on it; its protein half-life has been measured.
Gene: Protein-coding gene on chromosome 6 (75,749,175 to 75,919,537, forward strand). Ensembl gene ENSG00000196586.
Subcellular location: Golgi apparatus, trans-Golgi network membrane; Golgi apparatus; Nucleus; Cytoplasm, perinuclear region; Membrane, clathrin-coated pit; Cytoplasmic vesicle, clathrin-coated vesicle; Cell projection, filopodium; Cell projection, ruffle membrane; Cell projection, microvillus; Cytoplasm, cytosol; Cytoplasmic vesicle, autophagosome; Endosome; Cytoplasmic vesicle, clathrin-coated vesicle membrane (Isoform 3); Cytoplasmic vesicle, clathrin-coated vesicle membrane (Isoform 4)
Subcellular location (Human Protein Atlas): Nucleoplasm
Pathways (Reactome):
Signal Transduction: RHOBTB1 GTPase cycle; RHOBTB2 GTPase cycle; RHOU GTPase cycle
Neuronal System: Trafficking of AMPA receptors
Vesicle-mediated transport: Gap junction degradation
Gene Ontology:
Molecular function: actin filament binding; protein binding; actin binding; ADP binding; calmodulin binding; cytoskeletal motor activity; minus-end directed microfilament motor activity; ATP binding
Biological process: endocytosis; regulation of secretion; actin filament organization; actin filament-based movement; inner ear auditory receptor cell differentiation; inner ear morphogenesis; intracellular protein localization; intracellular protein transport; Rho protein signal transduction; septin ring organization; postsynaptic neurotransmitter receptor internalization; presynaptic modulation of chemical synaptic transmission
Cellular component: clathrin-coated endocytic vesicle; cytoplasm; cytoplasmic vesicle; endosome; extracellular exosome; filamentous actin; Golgi apparatus; membrane; nuclear membrane; nucleoplasm; nucleus; perinuclear region of cytoplasm; ruffle; actin cytoskeleton; actin filament; cell cortex; cytosol; endocytic vesicle; lysosomal membrane; plasma membrane; unconventional myosin complex; autophagosome; axon; brush border; clathrin-coated pit; and 14 more
Genetic constraint (gnomAD): Loss-of-function variants: 48 observed, 126.65 expected, observed/expected ratio (o/e) 0.38, 90% interval 0.3 to 0.48. The upper end of that interval is the gene's LOEUF score, 0.48, which puts it in group 2 of 6, group 1 being the genes least tolerant of losing a copy. Missense variants: 1,086 observed, 1,348.9 expected, observed/expected ratio (o/e) 0.81, 90% interval 0.76 to 0.85. Synonymous variants: 427 observed, 455.91 expected, observed/expected ratio (o/e) 0.94, 90% interval 0.86 to 1.01.
Gene-disease validity (ClinGen):
ClinGen rates the evidence that MYO6 causes each of these diseases.
nonsyndromic genetic hearing loss (autosomal dominant): Definitive.
Homologues: Orthologues: macaque MYO6 (99% identical), chimpanzee MYO6 (99% identical), rabbit MYO6 (98% identical), pig MYO6 (97% identical), guinea pig MYO6 (97% identical), mouse Myo6 (96% identical), rat Myo6 (96% identical), dog MYO6 (96% identical), tropical clawed frog myo6 (87% identical), zebrafish myo6b (82% identical), zebrafish myo6a (81% identical), Drosophila melanogaster jar (51% identical), and 1 more. Paralogues in human: MYO7A (25% identical), MYH2 (25% identical), MYO1C (25% identical), MYH8 (25% identical), MYO15A (25% identical), MYO1B (25% identical), MYO10 (25% identical), MYH1 (25% identical), MYH3 (25% identical), MYH4 (25% identical), MYH6 (25% identical), MYH7 (25% identical), and 32 more.
Diseases named in the same sentence as MYO6 in open-access papers:
MYO6 is named in the same sentence as 70 diseases in open-access papers, as found by Europe PMC text mining. Sharing a sentence is not in itself a finding about the gene and the disease. The quoted sentences say what the papers report.
deafness (35 papers, 2008 to 2025). An inherited or acquired condition characterized by the complete loss of the ability to hear from one or both ears. "Defects in myosin VI activity are known to cause genetic diseases such as deafness and cardiomyopathy." (PMID 38331992, 2024). "Consistent with our structural analyses, these deafness-associated mutations led to a mild yet significant increase in the ATPase activity of myosin VI." (PMID 38331992, 2024). "Loss of these functions, as observed in MYO6-deficient Snell’s waltzer mice and in humans with mutations in the MYO6 gene, contributes to various disease phenotypes, including deafness, astrogliosis, proteinuria, and hypertrophic cardiomyopathy." (PMID 38660538, 2024). "This implies the incomplete penetrance of MYO6 in deafness onset, or possibly cooperated with distinct genetic modifiers to cause deafness or CHD respectively." (PMID 38164514, 2023). "Among all the genes that can cause non-syndromic deafness, MYO6 is a very typical representative in terms of the complexity of the deafness mechanism." (PMID 37258513, 2023). "In initial assessment, we propose that the NM_004999.3 (MYO6): c.2377T>G (p.Trp793Gly) variant serves as the primary causative factor for deafness, while the second variant, NM_004999.3 (MYO6): c.2382G>T (p.Lys794Asn), exhibits weaker pathogenicity." (PMID 38274113, 2023). "The primary evidence for the association of myosin VI with the hearing process is based on the Snell’s waltzer mice, that exhibit deafness." (PMID 32066420, 2020). "Proteins such as SPARC and unconventional myosin-VI (Myo6), known to be associated with cochlear development, hearing, and deafness, were identified among these proteins." (PMID 30127667, 2018). "The Myo6 gene was first reported to be mutated in Snell’s waltzer mice that exhibited circling and headtossing behavior and deafness due to loss of hair cells." (PMID 27171474, 2016). "Mutations in Myo6, the gene encoding the (F‐actin) minus end‐directed unconventional myosin, myosin VI, cause hereditary deafness in mice (Snell's waltzer) and humans." (PMID 27111754, 2016). "In humans, defects in myosin VI also cause deafness and an inherited form of hypertrophic cardiomyopathy." (PMID 27474411, 2016). "Mutations in the human MYO6 gene are associated with a dominant nonsyndromic deafness called DFNA22 and a recessive form of hearing loss called DFNB37." (PMID 27171474, 2016). "In humans, the R1166X mutation causes deafness; however, the exact function of myosin VI in the hair cells of the inner ear and which specific myosin VI isoform is required is not fully understood." (PMID 27474411, 2016). "Our study of Korean patients with ADNSHL identified four novel mutations in the MYO6 gene that appear to be causally related to deafness." (PMID 25080041, 2014). "At least three mutations in Myo6 have been associated with non-syndromic deafness in humans probably because of disruptions to the structure and function of stereocilia." (PMID 23620821, 2013). "That the Myo6 gene functions in hearing is supported by overwhelming evidence, as mutations cause non-syndromic deafness in humans." (PMID 23620821, 2013). "The unconventional myosin VI, which when mutated causes hereditary deafness in mice (Snell's waltzer) and humans, is a protein responsible for actin-based motility." (PMID 21526224, 2011). "The identified mutation is a G694T transversion leading to an aspartic acid to tyrosine amino acid substitution at position 179, adding to the catalogue of Myo6 mutations that cause deafness and balance defects in mice and humans." (PMID 18833301, 2008). "Much of our information regarding myosin VI comes from studies in cell culture or mouse mutants with mutations leading to deafness." (PMID 18833301, 2008).
deafness (continued). "Therefore, it is necessary to systematically and carefully analyze the functional changes of synaptic transmission of IHCs on different MYO6 mutation mice models in order to fully and deeply reveal the deafness mechanism of Myosin VI gene mutation." (PMID 37258513, 2023). "Finally, we show that the L926Q deafness mutation disrupts Myo6 auto-inhibition and indirectly impairs proximal dimerization." (PMID 37872146, 2023). "MYO6, an unconventional myosin, has been previously associated with deafness." (PMID 29958461, 2018). "Understanding the functions of myosin VI within the cell and how it is regulated is now of utmost importance given the recent observations that it is associated with a number of human disorders such as deafness and cancers." (PMID 18068125, 2008). "Importantly, this is the first analysis of an myosin VI mutation in the CBD that causes deafness." (PMID 27474411, 2016). "Successful humanization of mouse models for deafness genes, like MYO6 and COCH, has yielded critical insights into the molecular mechanisms of hearing diseases." (PMID 40089864, 2025). "Of note, we identified a high impact frameshift mutation c.2751dup in MYO6 in 31 LVOTO patients, a variant that is associated with deafness." (PMID 38164514, 2023). "This approach has been recently used successfully to correct a semi-dominant mutation in the myosin VI gene, Myo6, using a mouse mutant the reproduce the human DFNA22 deafness mutation." (PMID 34778871, 2021). "The myo6 gene was reported to be involved not only in deafness, but also in mild symptoms of cardiac hypertrophy." (PMID 28077597, 2017). "In the present study, we analysed the subcellular localisation of the human deafness mutant R1166X, which leads to the deletion of 120 amino acids from the C-terminus of myosin VI." (PMID 27474411, 2016). "In the present study, we have analysed the cellular distribution of a human myosin VI deafness mutant (R1166X)." (PMID 27474411, 2016). "Mutations in myosin VI have been associated with autosomal-recessive (DFNB37) and autosomal-dominant (DFNA22) deafness in humans." (PMID 27474411, 2016). "Mutations in MYO6 and MYO1C are a major cause of deafness in humans, however, so far a detailed phenotypic analysis of the affected patient families for other pathologies related to dysfunctional autophagy have not yet been performed." (PMID 27146966, 2016). "This physically connected network contains two known non-syndromic deafness genes MYO6 (MIM ID 600970) and TMPRSS3 (MIM ID 605511)." (PMID 21980309, 2011). "Understanding how myosin VI is regulated has importance for developing therapeutic targets for combating human diseases such as cancer, deafness and cystic fibrosis." (PMID 18068125, 2008). "Most compelling, mutations in the myosin VI gene are associated with a dominantly inherited form of human hearing loss, DFNA22, a recessively inherited form of human deafness, DFNB37, and hypertrophic cardiomyopathy." (PMID 18833301, 2008). "In conclusion, our results suggest that compared with wild-type mice, the ribbon synaptic transmission function of IHCs from different Myosin VI mutant mice is down-regulated, further revealing the physiological and pathological mechanism of Myosin VI in hearing and deafness." (PMID 37258513, 2023). "This unique property may explain the large number of phenotypes observed in the myosin VI knockout mouse, the Snell's waltzer mouse, which include deafness and profound gliosis." (PMID 27474411, 2016). "In conclusion, our characterisation of the human myosin VI deafness mutant (R1166X) suggests that defects in cargo binding may leave myosin VI in a primed/activated state with an increased actin-binding ability." (PMID 27474411, 2016). "The human gene MYO6, located on chromosome 6q13, maps with the deafness locus DFNA22 and DFNB37." (PMID 25939269, 2015).
deafness (continued). "Hence, it is plausible that the first mutation, c.2377T>G in MYO6 (NM004999), and the corresponding p.Trp793Gly substitution, may be the primary causative factor for the observed deafness, given its rarity and the strong predictions of pathogenicity." (PMID 38274113, 2023). "An myosin VI mutation (3496C > T) that causes deafness in Pakistani families leads to a premature stop in the C-terminal cargo-binding tail domain (at R1166X) and loss of the WWY motif, the binding site for myosin VI adaptor proteins, including Dab2, LMTK2 and Tom1/L2." (PMID 27474411, 2016). "MYO6 (OMIM *600970) encodes for nonconventional myosin VI and is mutated in autosomal dominant deafness DFNA22, with or without hypertrophic cardiomyopathy, and autosomal recessive deafness DFNB37." (PMID 34562878, 2021). "MYO6 is required for the proper maturation of inner hair cell ribbon synapses and it has been shown to interact with DFNB9 (responsible for a recessive form of deafness) via the globular domain." (PMID 32066420, 2020). "As ten of the 54 regions not excluded by linkage analysis harbored known deafness genes, coverage of all exons and exon–intron boundaries of these genes, including MYO6 (MIM: 600970), was manually checked to be at least 10×." (PMID 29754270, 2018).
hearing loss (34 papers, 2008 to 2025). "These high priority genes, including MPHOSPH8, MYO18A, TRIOBP, OTOGL, TNC, and MYO6, were previously implicated in hearing loss, balance, and cochlear function, and were significantly enriched in common variant studies of hearing loss." (PMID 38943082, 2024). "Our findings substantiate the pivotal role of MYO6 in the etiology of early-onset hearing loss, unveiling a facet of monogenic compound heterozygosity." (PMID 38274113, 2023). "Even though marginal, quantitative analyses reached statistical significance, suggesting the POU4F3 variant regulates MYO6 expression in the hearing loss pathology." (PMID 37537203, 2023). "Since we observed MYO6 expression significantly dysregulated in the hearing-loss group, we further validated by RT-qPCR." (PMID 37537203, 2023). "Prior investigations have documented that most MYO6-associated hearing loss presents as sensorineural, bilateral, and progressive." (PMID 38274113, 2023). "Statistically significant downregulation was seen in Bdnf and MYO6 in the hearing loss group, compared to the hearing loss group." (PMID 37537203, 2023). "Among more than 100 genes that cause non-syndromic hearing loss, myosin VI (MYO6) is typical in terms of the complexity of underlying mechanisms, which are not well understood." (PMID 37258513, 2023). "We identified two variants, c.[2377T>G; 2382G>T] p.[Trp793Gly; Lys794Asn] in MYO6 as strong candidates responsible for the observed progressive hereditary hearing loss." (PMID 38274113, 2023). "COCH Cys542Phe and MYO6 His246Arg are known pathogenic variants, and consistent with this, we observe almost all carriers presenting hearing loss." (PMID 35661827, 2022). "In this study, to clarify the frequency and clinical characteristics of hearing loss caused by MYO6 gene mutations, a large-scale genetic analysis of Japanese patients with hearing loss was performed." (PMID 32143290, 2020). "We have presented a family with a complex phenotype of SCN and hearing loss that can be attributed to AD variants in two genes, GFI1 causing SCN, and MYO6 leading to hearing loss." (PMID 32066420, 2020). "The novel MYO6 I1176L variant segregated with hearing loss in all but one individual (V-5) who displayed clinically unconfirmed mild hearing loss." (PMID 32066420, 2020). "Despite its importance in the inner ear, a limited number of MYO6-associated hearing loss cases have been published." (PMID 32143290, 2020). "Among these 33 MYO6-associated hearing loss families, seven families were reported in our previous paper." (PMID 32143290, 2020). "Analysis of the data for variants in genes associated with non-syndromic hearing loss, identified a novel single nucleotide variant in MYO6 (NM_004999.4, c.3526A > C/p.Ile1176Leu, I1176L), a gene that has previously been associated with AD hearing loss." (PMID 32066420, 2020). "An unconventional myosin encoded by the myosin VI gene (MYO6) contributes to hearing loss in humans." (PMID 28832620, 2017). "Here we report Turner (Tur), a novel ENU-induced dominant point mutation c.820A>T in exon 8 of the Myo6 gene that changes amino acid Asn200 to Ile (p.N200I) in the motor domain, causing headtossing and circling behavior and hearing impairment." (PMID 27171474, 2016). "Here, we characterise an myosin VI nonsense mutation (R1166X) that was identified in a family with hereditary hearing loss in Pakistan." (PMID 27474411, 2016). "A total of 11 proteins, including cochlin, myosin VI, and myosin IX, were identified that when defective are associated with hearing impairment or loss." (PMID 22942697, 2012). "Myosin VI is an actin-based molecular motor that has been previously shown to underlie hereditary hearing loss in both human and mice (see Introduction)." (PMID 18833301, 2008).